FAM246B (family with sequence similarity 246 member B)
Gene: Protein-coding gene on chromosome 22 (18,633,984 to 18,634,682, forward strand). Ensembl gene ENSG00000286175.
Homologues: Orthologues: mouse Fam246a (72% identical), rat LOC120095536 (70% identical). Paralogues in human: FAM246A (98% identical), FAM246C (42% identical).